TLR2 (toll like receptor 2)
Diseases named in the same sentence as TLR2 in open-access papers (continued):
Sharing a sentence is not in itself a finding about the gene and the disease.
infection (continued). "We expected a weaker ability since activation of TLR2-deficient BMDC upon infection with the bacterium in vitro was impaired as analyzed by IL-12p40 and TNF secretion and induction of NF-κB." (PMID 22096480, 2011). "Although we have shown that TLR2−/− mice are more susceptible to i.n. infection with F. tularensis subsp." (PMID 19936231, 2009). "Of these, the only two in vivo studies, one exploring an intranasal infection model in mouse and the other an intradermal model, came to different conclusions regarding the TLR2-dependence of mouse susceptibility to F. tularensis LVS infection." (PMID 19936231, 2009). "Studies with Candida albicans have shown that TLR2−/− mice are more resistant to this infection, a fact associated with the decreased release of anti-inflammatory cytokines, such as IL-10." (PMID 19229338, 2009). "Parameters of lung inflammation in TLR2 KO and WT mice 24, 48 and 72 h after infection with pneumolysin-deficient S. pneumoniae PLN." (PMID 17711480, 2008). "And TLR4 is not important for protective immunity against experimentally induced melioidosis, whereas TLR2 is associated with the growth and dissemination of the infection, significantly contributing to distant organ injury and lethality." (PMID 17676990, 2007). "Polymorphisms in the TLR2 gene may affect its expression or function, thereby modulating host responses to infection." (PMID 41503064, 2025). "To determine whether the reduced expression of tlr2 and tlr4 following infection of zebrafish with the Δhcp2 strain is associated with PGN and LPS, we quantitatively analyzed the LPS and PGN content of V. alginolyticus." (PMID 41230815, 2025). "Moreover, a study conducted in Iran revealed that the TLR2 Arg677Trp polymorphism was associated with a greater likelihood of infection among individuals exposed to Mycobacterium tuberculosis." (PMID 41295183, 2025). "The influence of TLR2 variants could be more evident in infections involving highly virulent H. pylori strains, particularly those expressing CagA or VacA." (PMID 41503064, 2025). "Polymorphisms in the TLR2 gene may affect susceptibility to these infections, with certain variants associated with an increased risk of invasive fungal disease in immunocompromised patients." (PMID 41295183, 2025). "However, in vitro infection of macrophages deficient in TLR2, TLR4, and MyD88 by L. amazonensis is higher than wild-type counterparts." (PMID 37000792, 2023). "Our results suggest that decreased IL-10 production during GBS infection in TLR2/4-deficient mice reduces the severity of ascending infection and may promote bacterial clearance." (PMID 37747229, 2023). "Notably, we observed that IL-10 and IL-10-expressing macrophages were significantly increased in the uterine tissues of WT mice compared with TLR2/4-deficient mice, during infection with HylB-proficient GBS in vivo." (PMID 37747229, 2023). "Similarly, a decreased expression level of TLR2-encoding genes of N. aperta was decreased at later infection stage, and up-regulated genes were significantly enriched in some metabolic and biosynthetic processes." (PMID 38017557, 2023). "Differences in the genetic background of the mice and the bacteria used, as well as of the infection protocol employed, could be the cause of the discrepant results observed regarding the role of TLR2 in the protection against TB in mice." (PMID 37787569, 2023). "Increased infection, inflammation and mortality was also observed in TLR2-deficient mice infected with wild-type C. muridarum in the lung; evidence for the importance of plasmid-dependent TLR2 activation in controlling lung infection and preventing death." (PMID 37662000, 2023). "Interleukin-10 (IL-10) and IL-10-expressing macrophages were significantly increased in the uterine tissues of WT mice during infection with HylB-proficient GBS compared with those of TLR2/4-deficient mice, and this likely promotes immune suppression and GBS dissemination." (PMID 37747229, 2023).
infection (continued). "Based on our results, the higher overexpression of TLR2 could be a dominant cause of multiple tissue injuries and high mortality in gibel carp post infection with CyHV-2." (PMID 38003793, 2023). "Compared to wildtype pups, TLR2-deficient pups inoculated with Group B Streptococcus at P2 were not susceptible to sepsis and did not produce increased amounts of IL-10 associated with damaging inflammation in wildtype pups at 24 h after infection (P3)." (PMID 37375099, 2023). "To determine whether the loss of both TLR2 and TLR9 alters bone homeostasis during infection, we performed μCT on infected femurs from WT and Tlr2/9−/− mice collected at 14 dpi." (PMID 36226943, 2022). "Additionally, TLR1 and TLR2 participate in the defence against colonisation/infection by C. albicans, with deficiency of these receptors leading to dissemination of the yeast." (PMID 35630457, 2022). "However, the exact mechanism of TLR2 or TLR4 polymorphisms in the pathogenesis of C. difficile colonization or infection warrants further examination." (PMID 34322122, 2021). "At the higher temperature of 37°C associated with mammalian infection, TLR2 was primarily activated with concurrent suppression of TLR4 activation that coincided with the biosynthesis of tetra- or penta-acylated modified forms of lipid A as previously reported." (PMID 34888257, 2021). "Regulating TJ integrity by TLR2 expression of probiotics might be the possible mechanism on suppressing excessive apoptosis induced by pathogenic infection." (PMID 31949265, 2020). "DENV infection modulates TLR2 expression on monocytes, which depending on their co-stimulatory markers contribute to infection-mediated inflammatory responses that may underlie severe disease development." (PMID 32576819, 2020). "In early control of cranial biofilm infection spread, TLR2 is associated with macrophage IL-1β pro-inflammatory cytokine production, but this signaling was insufficient to clear infection, perhaps due to established infection manipulation of the macrophage response." (PMID 33542723, 2020). "Interestingly, infection with L. monocytogenes decreased Siglec-E expression in all groups except for TLR2-deficient neutrophils, which showed increased expression." (PMID 32889432, 2020). "In order to combat infection with this multi-resistant mycobacterium, our goal here was to evaluate the vaccine and diagnostic potentials of a still crude cell envelope fraction, TRL2eF, showing a high TLR2-stimulating activity." (PMID 32984067, 2020). "TLR2-deficient mice expressed significant IL-10 following infection with Δhly." (PMID 32634175, 2020). "Although our in vitro and in vivo studies showed that TLR2 is critical for T. congolense-induced production of proinflammatory cytokines in macrophages, we found that deficiency of TLR2 (as seen in TLR2−/− mice) results in increased susceptibility to the infection." (PMID 31824484, 2019). "Indeed, a double TLR2/9 knockout mouse was more susceptible to infection than single knockout animals." (PMID 31114761, 2019). "In addition to the proinflammatory response, TLR2 has been shown to contribute to IFN-I production, with mice deficient for TLR2 having significantly reduced bioactivity of IFN-I in the serum following LCMV-WE infection." (PMID 30791575, 2019). "To test whether the TLR2 polymorphism influences variation in the susceptibility to infection with B. afzelii, we challenged pathogen-free, lab-born individuals of known TLR2 genotype with B. afzelii-infected ticks." (PMID 31040326, 2019). "Furthermore, TLR2- and MyD88-deficient mice developed increased bacterial burden after intratracheal infection with C. burnetii." (PMID 30800124, 2019). "Interestingly, regarding the innate immune receptors associated with IL-12 response during several infections, the extracellular leucine-rich repeat domains of TLR2 and TLR4 contain four and nine N-glycans, respectively." (PMID 31226171, 2019).
infection (continued). "In addition, NF-κB target genes (i.e., C3, Chi3l1, Fas, Gadd45β, Hmox1, Ptx3, Saa3, Tlr2) were abundant in the DEGs in which upregulation during infection was impaired by CCR5-deficiency." (PMID 31506064, 2019). "Similarly, infection with Anaplasma phagocytophilum, another obligate intracellular bacterium that infects neutrophils and causes human anaplasmosis, triggers TLR2 signals which induce secretion of proinflammatory cytokines via NF-κB." (PMID 31134081, 2019). "As an answer to these questions, the infection of mice deficient for Toll-like receptor 2 (TLR2), TLR4, IL-10, arachidonate 5-lipoxygenase (ALOX5), or arachidonate 15-lipoxygenase (ALOX15) with the M. tuberculosis Δnrp strain showed the same phenotype as WT mice." (PMID 30381350, 2018). "Interestingly, the diminished IL-8 responsiveness of COPD alveolar macrophage to NTHi infection has a strong association with the carriage of TLR9 (T1237C) polymorphism instead of TLR2 (Arg753Gln), TLR4 (Thr399Ile; Asp299Gly), and TLR9 (T1486C)." (PMID 30455693, 2018). "As infection with the gastric pathogen H. pylori has also been associated with MS, the TLR2-stimulating capacity of H. pylori lysate was assessed, confirming that this organism also contains abundant TLR2-stimulants." (PMID 29593720, 2018). "Since SLC11A1+ B6 mice were resistant to intranasal LVS infection, we wanted to determine if Slc11a1 expression could compensate for the loss of TLR2." (PMID 28360906, 2017). "The deranged phagocytizing capacity is highly associated with the reduced TLR2 expression on monocytes, and may provide a new therapeutic target to improving phagocytosis during infection." (PMID 29125848, 2017). "The expression level of TLR2 is closely associated with lipid oxidation and inflammation reactions, and also plays an important role in triggering innate and adaptive immune responses against infection, thereby protecting the host from disease." (PMID 28078083, 2017). "Despite these considerations, it has been shown in mice hydrodynamically injected/transduced with AAV-HBV, that the depletion of liver macrophages/monocytes, or the transduction of TLR2-deficient mice, was associated with a faster clearance of infection via a specific CD8+ T-cell response." (PMID 28452930, 2017). "As we also observed a loss of protection from HSV-2-induced disease in our super-infection model when we replaced live chlamydiae with UV-irradiated C. muridarum, TLR2 may be involved in eliciting protection from subsequent HSV-2 challenge." (PMID 26726882, 2016). "Minor genotype TLR2 rs5743708 GA/AA was associated with infection in this subset." (PMID 27725770, 2016). "This indicated that the release of chronic inflammation factors caused by infection with HCMV may be achieved via the TLR2 signaling pathway in the tumor microenvironment, thereby further inducing cell malignancy." (PMID 25435993, 2015). "Importantly, TLR2-deficient mice were shown to be susceptible to infection with very high doses of T. gondii, although they mount an unimpaired immune response when infected with conventional parasite loads." (PMID 26528819, 2015). "In addition, infection with high doses of Mycobacterium tuberculosis resulted in rapid mortality in TLR2-deficient mice." (PMID 26528819, 2015). "Such p38 MAPK-mediated suppression of TLR4 and TLR2 signaling may protect against an overwhelming immune reaction but may also lead to a higher risk of infection for the fetus and newborn." (PMID 25530682, 2014). "Activation of BMMφ with the TLR2/6 agonist FSL-1 resulted in upregulation of the CRAMP-encoding gene in a similar way to infection with M. avium, suggesting that mycobacterial infection might induce Camp expression in a TLR2-dependent manner." (PMID 25400920, 2014). "Additionally, it is also possible that the flourishing bacteria in the livers of TLR2-deficient mice at the late phase of infection further accelerate pro-inflammatory cytokine induction." (PMID 24058538, 2013).
infection (continued). "Furthermore, IL-10 levels were hardly detected in the blood of TLR2-deficient animals during infection." (PMID 24058538, 2013). "Although TLR2-deficient mice exhibited hepatic levels of TNF-α equivalent to those in WT mice at 6 h post-infection, a subsequent decrease in hepatic TNF-α levels was significantly delayed in TLR2-deficient mice with 7.7-fold higher levels at 3 d post-infection (vs. WT mice)." (PMID 24058538, 2013). "Moreover, blood TNF-α was also abundantly produced in the TLR2-deficient mice and peaked to levels 2.3-fold higher than those in WT mice at 6 h post-infection." (PMID 24058538, 2013). "Theysuggested a pathogenic role for TLR2 during someintrauterine infections." (PMID 24520479, 2013). "In addition, mouse infection models with several different viruses have shown deficiencies in viral clearance in mice with a targeted deletion in TLR2." (PMID 23853595, 2013). "Despite the extensive remodeling of macrophage functions following TLR2 signaling, TLR2-deficient mice are able to resist acute Mtb infection and develop an appropriate secondary immune response following a low dose aerosol infection." (PMID 23785280, 2013). "Similarly, in this study, TLR2-deficient mice showed enhanced susceptibility and all succumbed to S. aureus infection within 4 d post-infection as well as a high bacterial burden in their livers." (PMID 24058538, 2013). "In summary, results obtained in this study reveal that infection of mice by highly pathogenic strains of S. suis may follow TLR2-dependent or independent pathways depending on the strain." (PMID 23724118, 2013). "Indeed, studies in TLR2-deficient mice suggest a phenotype intermediate between MyD88-deficient and control mice, indicating that TLR2 participates in the control of infection." (PMID 23940747, 2013). "A low basal expression of TLR2 might be associated with the particular susceptibility of neonates for infections with gram-positive pathogens." (PMID 23431318, 2013). "Inoculation with S. aureus resulted in rapid neutrophil infiltration into the hepatic sinusoid of both the WT mice and TLR2-deficient mice within the first 6 h post-infection; at 2 d post-infection, an increase in macrophages was noted in the livers of the 2 mouse groups." (PMID 24058538, 2013). "However, IL-10 release attenuated in the livers of TLR2-deficient mice from 1 d post-infection and significantly reduced by 70% at 3 d post-infection (vs. WT mice)." (PMID 24058538, 2013). "Similarly, Gram-stained liver sections of mice at 3 d post-infection revealed that a large number of S. aureus were present in clusters in the TLR2-deficient mice, while the bacteria were dispersed at infectious foci with few clusters in WT mice." (PMID 24058538, 2013). "Since myocyte lysis is induced by either virus replication or host immune response to the virus, infection should release cardiac myosin into the local environment, causing one to anticipate that TLR2 could have a major impact on pathogenicity." (PMID 23241283, 2012). "Therefore, in the immune competent host, there are other components of the immune system than the spleen that can provide a sufficient backup mechanism for TLR2 deficiency in the defense against intrapulmonary infections with S. pneumoniae." (PMID 22721450, 2012). "Therefore, other components can provide sufficient backup mechanisms for TLR2 deficiency in the defense against intrapulmonary infections with S. pneumoniae of the otherwise immune competent host." (PMID 22721450, 2012). "By comparing the differences in TLR2-dependent responses during infection by arenaviruses of differing pathogenic potential for humans and non-human primates in vitro, we have provided a possible explanation for the development of severe disease in LASV infection." (PMID 23202459, 2012).
infection (continued). "Interestingly, B-cells appeared to be decreased in response to infection in the TLR2-deficient mice compared to wild type mice when analyzed by this method, although immunohistochemistry demonstrated the formation of B-cell aggregates into areas of BALT." (PMID 21695078, 2011). "Since the infection of TLR2/4 double-deficient mice with C. pneumoniae generated even more CD4+IFNγ+ T-cells, we conclude that in vivo antigen-presenting cells are not impaired in their ability to activate antigen-specific T-cells in the absence of TLR2 and TLR4." (PMID 22096480, 2011). "Moreover, IFN-γ, IL-12 and IL-17, which have been shown to be required for bacterial clearance, were also elevated in the TLR2-deficient mice, possibly facilitating resolution of the infection in spite of more severe disease." (PMID 21695078, 2011). "The trend towards increased weight loss following challenge that we observed in the TLR2-deficient mice suggested that they might have suffered more severe inflammation during the course of infection compared to the controls." (PMID 21695078, 2011). "However, upon infection the frequency of these cells was almost 3-fold higher in wild type compared to TLR2/4 double-deficient mice." (PMID 22096480, 2011). "Intracellular staining for IFNγ revealed that the frequency and absolute number of CD4+ T-cells producing the cytokine upon re-stimulation with C. pneumoniae were higher in TLR2/4 double-deficient when compared to wild type mice especially day 9 post infection." (PMID 22096480, 2011). "Models of infection with a high virulence strain may cause very significant differences in fungal burden and inflammatory cytokine production between control and TLR2−/− mice which make the results very difficult to interpret." (PMID 21935459, 2011). "However, upon infection TLR2/4 double-deficient mice displayed a lower frequency of CD4+CD25+Foxp3+ regulatory T-cells in vivo and the frequency of regulatory T-cells was inversely related to the frequency of CD4+IFNγ+ T-cells." (PMID 22096480, 2011). "We found that while both mouse strains cleared the infection over time in a similar manner, the disease was more severe in TLR2-deficient mice, and these mice developed significantly higher lung cytokine levels with exaggerated neutrophil and T-cell influx in the lungs." (PMID 21695078, 2011). "As a supporting example, previous studies indicate that TLR2 expression may be linked to mucin production by epithelial cells and clearance of the human pathogen, M. pneumoniae, in a mouse infection." (PMID 20505832, 2010). "Thus the basis for the difference in susceptibility to infection observed between MyD88−/− and TLR2−/− mice requires further study." (PMID 19936231, 2009). "As TLR2 is expressed on the apical surfaces of both tissues, TLR2 blockades may be useful for reducing hyperinflammation caused by Gram-positive pathogens when combined with appropriate antibiotics to adequately manage infection." (PMID 40426880, 2025). "Although biological plausibility and previous findings suggested a potential role for TLR2 in host immune responses to H. pylori, our pooled analyses across multiple genetic models did not reveal any statistically significant association between either polymorphism or infection risk." (PMID 41503064, 2025). "Therefore, it can be proposed that TLR2 may have a detrimental effect on the progression of E. granulosus infection and may also enhance the immune response associated with this infection via the TLR2/MyD88/NF-κB signaling pathway." (PMID 39199394, 2024). "Therefore, it could be that the different responses to wounding and infection in the tlr2 mutant are caused by mitochondrial dysfunction due to the aberrant expression of genes involved in metabolism." (PMID 36829598, 2023). "However, other studies claimed that TLR2 deficiency may be harmful and implicated in gastric carcinogenesis, because weaken immune response would take place and infection would increase." (PMID 33525650, 2021).